GRB7 (growth factor receptor bound protein 7)
Diseases named in the same sentence as GRB7 in open-access papers (continued):
Sharing a sentence is not in itself a finding about the gene and the disease.
cancer (continued). "By imaging the same site in the same cancer tissue, we found that the expression of GRB7 and CD31 was significantly correlated." (PMID 34783299, 2021). "Taken together, the acquisition of the malignant cancer cell phenotype is enhanced with GRB7 overexpression." (PMID 32737994, 2020). "In an era of advances in developing molecular‐targeted therapy against SH2 domains in cancers, our preclinical studies endorse the future development of GRB7 inhibitors and their potential clinical use in OAC patient treatment." (PMID 32737994, 2020). "Among these significant gene sets were several cell-signaling pathways, including the ERBB3 pathway, the PI3K/AKT signaling in cancer pathway and a pathway related to GRB7 events in ERBB2 signaling." (PMID 33154357, 2020). "Consistently, knockdown or inhibition of Grb7 expression or the specific kinase activity of Grb7-mediated downstream signals abrogates Grb7-mediated cancer migration." (PMID 31083325, 2019). "Consistently, inhibition of the specific kinase activity of Grb7-mediated downstream signals significantly reduces Grb7-mediated cancer invasion." (PMID 31083325, 2019). "Of note, the detailed regulatory mechanisms, side effects, proper dose, tolerability, as well as treatment-induced resistant cancers against molecules targeting Grb7 or in combination with protein tyrosine kinase-targeting agents/drugs remains to be evaluated." (PMID 31083325, 2019). "FAK is a critical upstream factor in Grb7-mediated signaling pathways that enable activation by growth factor receptors or integrins during cancer development." (PMID 31083325, 2019). "In particular, critical roles of Grb7 in erythroblastic leukemia viral oncogene homolog (ERBB) family-mediated cancer development and malignancy have been intensively evaluated." (PMID 31083325, 2019). "In ERBB2 positive cancer cells, knockdown of Grb7 has been found to decrease integrin-mediated RAC1 activation as well as integrin-mediated cell movement." (PMID 31083325, 2019). "Here, we review the molecular, functional, and clinical aspects of Grb7 in ERBB family-mediated cancer development and malignancy with the aim to reveal alternative and effective therapeutic strategies." (PMID 31083325, 2019). "Clinical studies have indicated that upregulation of Grb7 is significantly correlated with the recurrence and low survival of patients with cancer, suggesting critical roles of Grb7 during cancer development and treatment." (PMID 31083325, 2019). "As numerous studies have illustrated, Grb7 amplifies oncogenic signals to promote cancer development, thereby highlighting that targeting both Grb7 and Grb7-amplified oncogenic signals provides a synergistic therapeutic effect on anti-cancer therapy." (PMID 31083325, 2019). "Grb7 as a functionally multidomain adaptor is essential for cancer development by binding to phospho-tyrosine-related oncogenic signaling molecules to amplify oncogenic signal transduction cascades." (PMID 31083325, 2019). "Based on preclinical and clinical studies, the upregulation of Grb7 in numerous human cancers highlights Grb7 as a potential prognostic marker and a therapeutic target." (PMID 31083325, 2019). "Functionally, the SH2 dominant-negative fragment of Grb7 ablates the fibronectin-mediated tyrosine phosphorylation of Grb7, resulting in a reduction of cancer migration." (PMID 31083325, 2019). "The protein stability, protein binding ability, and phosphorylation of Grb7 are also critical for Grb7- or ERBB family/Grb7- mediated cancer proliferation." (PMID 31083325, 2019). "Of note, tyrosine phosphorylation-deficient mutants of Grb7 have been shown to regulate the phosphorylation of AKT, ERK1/2, and paxillin, and subsequently ablate cancer proliferation and anchorage-independent growth." (PMID 31083325, 2019). "Understanding the detailed regulatory mechanisms of Grb7 in cancer development can provide alternative methods for cancer therapy." (PMID 31083325, 2019).
cancer (continued). "Due to the upregulation of Grb7, which is correlated with recurrence and low survival in patients with cancer, combination treatments targeting both Grb7 and oncogenic signals provide potential therapeutic strategies." (PMID 31083325, 2019). "Several empirical studies showed that Grb7 associates with ERBB2 and facilitates ERBB2-mediated cancer migration and proliferation." (PMID 31083325, 2019). "Grb7- and ERBB family/Grb7-mediated signal transduction cascades have been reported to facilitate cancer cell survival through the regulation of mitochondria-associated apoptotic pathways." (PMID 31083325, 2019). "Collectively, the molecular mechanisms and cellular functions of Grb7 in ERBB family-mediated cancer have provided valuable basic and clinical information for targeting Grb7 or Grb7-amplified oncogenic signals to improve the outcomes of human cancer cases." (PMID 31083325, 2019). "In particular, the multifunctional features of Grb7 have been emphasized as being involved in ERBB family-mediated cancer malignancy." (PMID 31083325, 2019). "In agreement with the clinical relevance of the Grb7 expression level in cancer malignancy, overexpression of Grb7 was significantly correlated with the lymph node-positive status of cancer metastasis." (PMID 31083325, 2019). "Reportedly, GRB7v, a variant of Grb7 that displays a substitution of the SH2 domain with a hydrophobic sequence, has also been shown to greatly increase cancer proliferation as well as anchorage-independent growth by regulation of ERK signaling." (PMID 31083325, 2019). "Numerous empirical studies have verified that ErbB family/Grb7-regulated signaling contributes to the malignant characteristics of cancers, emphasizing Grb7 as a promising prognostic marker and a potential therapeutic target in ERBB family-mediated cancer." (PMID 31083325, 2019). "The G7-18NATE peptide, in particular, has provided significant proof-of-concept evidence that inhibition of Grb7 via blocking its SH2 domain has effective anti-cancer effects in cells and animal models." (PMID 31627265, 2019). "Based on the critical role of Grb7 in cancer, a Grb7 peptide targeting the specific Grb7 SH2 phosphotyrosine binding site that prevents Grb7-mediated signaling appears to be a promising targeted therapeutic candidate against malignant cancers." (PMID 31083325, 2019). "For instance, the RA-PH domain of Grb7 interacts with the four and a half LIM domains isoform 2 (FHL2), a cancer-associated transcription regulator." (PMID 31083325, 2019). "Due to Grb7 being a potential therapeutic target in cancer, these studies improved the efficiency of the Grb7 inhibitor and promoted the development of Grb7-targeted therapies." (PMID 31083325, 2019). "Grb7 overexpression has been determined as an independent indication of poor prognostic cancer progression." (PMID 31627265, 2019). "Functionally, the formation of the FAK/Grb7 complex or FAK-mediated Grb7 phosphorylation are required for cancer malignancy, such as cell migration, proliferation, and anchorage-independent growth." (PMID 31083325, 2019). "As expected, short hairpin RNA-mediated knockdown of GRB7 expression reduces gap closure migration of cancers in response to the EGF treatment." (PMID 31083325, 2019). "Together, these studies indicate high GRB7 expression is a highly significant predictor for recurrence after cancer treatment." (PMID 31083325, 2019). "Sequence analysis identifies the structural conservation of the RA domain in the Grb7 adaptor protein family, suggesting the potential ability of Grb7 to interact with small GTPases of the Ras superfamily and in regulating Ras-mediated cancer progression." (PMID 31083325, 2019). "Together, these studies suggest that combination treatment with shRNA or peptides targeting Grb7 and chemotherapy, or targeted therapy improves the efficiency of anti-cancer therapy." (PMID 31083325, 2019).
cancer (continued). "First, multiple genes already used in the clinic as cancer biomarkers encode proteins within the Src signature, including Her2, MUC16, PLAU, SERPINE1, Aurora A kinase, Cyclin B1, GRB7 and Ki-67." (PMID 29904729, 2018). "Grb7 has been identified as a therapeutic target due to its role in the progression of a number of cancers including breast, pancreatic, ovarian and oesophageal cancers." (PMID 29018805, 2017). "The current study has utilised ring closing metathesis of O-allylserine residues to staple the cyclic peptide G7-18NATE targeted to the SH2 domain of Grb7 involved in cancer progression." (PMID 27257138, 2016). "Although the clinical relevance of Pin1 and Grb7 expression during oncogenesis remains to be examined, both molecules have been known to be often involved in cancer progression." (PMID 27658202, 2016). "HER2+ cancers are frequently associated with amplification and over-expression of the ERBB2 and GRB7 genes, both from the 17q12–21 amplicon." (PMID 22343619, 2012). "Emerging evidence has reported that aberrant upregulation and activation of GRB7, ERK as well as FOXM1 are closely associated with aggresivenesss of human cancers." (PMID 23285101, 2012). "We and others have previously reported that GRB7 is frequently overexpressed and promotes cell proliferation, cell migration and cell invasion of human cancers." (PMID 23285101, 2012). "Previous studies have shown that constitutive activation of ERK activity or increased expression of GRB7 and FOXM1 are closely associated with tumorigenicity of various human cancers." (PMID 23285101, 2012). "Emerging evidences have reported that GRB7 is overexpressed and usually accompanied with overexpression of erbB2 in human cancers." (PMID 23285101, 2012). "Three genes (P-cadherin, v-kit, FOXC1) were reported by the authors to be associated to a genes cluster over-expressed in the basal-like carcinomas and three genes (PTEN, Her2 and GRB7) to a genes cluster over-expressed in the Her2+ carcinomas." (PMID 21047405, 2010). "Grb7 is thus an important candidate for the development of inhibitors that block aberrant Grb7 downstream signaling in cancer progression." (PMID 17894853, 2007). "The Grb7 SH2 domain has been identified as a potential target for the development of agents to reduce the invasive potential of cancer cells in which Grb7 is overexpressed." (PMID 17894853, 2007). "Due to the implication of Grb7 in cancer cell progression, an inhibitor specific for Grb7 SH2 domain has been developed that targets the Grb7 SH2 pY peptide binding site." (PMID 17894853, 2007). "G7-18NATE thus represents the first specific inhibitor of Grb7 and the first stage in the development of a potential anti-cancer therapeutic." (PMID 17894853, 2007). "The structural basis for their interaction has been modeled based on the biophysical data and represents a starting point for the development of second generation inhibitors of Grb7 based cancer cell migration and proliferation." (PMID 17894853, 2007). "Recent data suggest that upregulation of Grb7 impacts on both the proliferative and invasive potential of the cancer cells." (PMID 17894853, 2007). "Conversely, formation or disassembly of stress-induced condensates may be regulated by kinases as in the case of Grb7 phosphorylation in carcinoma cells." (PMID 41166398, 2025). "The crucial role of GRB7 in cancer prognosis was illustrated in many studies." (PMID 39742197, 2024). "This highlights the potential of GRB7 as a prognostic biomarker in these cancer types." (PMID 39742197, 2024). "Materials and methods: GRB7 expression across different cancers was evaluated using the Tumor Immune Estimation Resource (TIMER), Gene Expression Profiling Interactive Analysis (GEPIA), and the University of Alabama at Birmingham Cancer Data Analysis Portal (UALCAN)." (PMID 39742197, 2024).
cancer (continued). "GRB7’s preferential expression in malignant cells highlights its significance in the biology of cancer and bolsters the possibility that it could be useful in enhancing the effectiveness of immunotherapy." (PMID 39204147, 2024). "GRB7 has been found to amplify oncogenic signals, promoting cancer development." (PMID 39360313, 2024). "Specifically, higher levels of GRB7 may promote the infiltration of B cells, CD8+ T cells, and macrophages while reducing macrophage presence in some cancers, suggesting that GRB7 plays a complex role in shaping the immune landscape across different cancers." (PMID 39742197, 2024). "Furthermore, based on TCGA data, we discovered that GRB7 is overexpressed in the majority of tumor tissues and is primarily expressed in malignant cells across a range of cancer types." (PMID 39204147, 2024). "The ERK signaling is one of the important pathways associated with proliferation and migration in various cancers, through western blot assay, we found that the levels of p-ERK in AGS and MGC-803 cells were significantly increased by GRB7 overexpression." (PMID 39360313, 2024). "Clinical data from various cases reveal that GRB7 expression level is often negatively correlated with patient prognosis, suggesting a noteworthy link between GRB7 and cancer development." (PMID 39360313, 2024). "Further analysis of the role of GRB7 in cancer could lead to the development of new therapeutic approaches." (PMID 39742197, 2024). "Previous findings have suggested that GRB7 was up-regulated in breast, blood, pancreatic, and esophageal cancer, and may contribute to the invasive potential of cancer cells." (PMID 38129809, 2023). "GRB7 was involved in the occurrence and development of various malignant tumors." (PMID 36642706, 2023). "The relationship between GRB7 expression and cancer development is worth exploring." (PMID 36686796, 2022). "GRB7 protein was expressed more highly in cancer tissues than in adjacent tissues." (PMID 36686796, 2022). "In addition to being initially identified as an EGFR binding partner, GRB7 has also been reported to interact with small GTPases in the Ras superfamily and regulate Ras-mediated cancer progression." (PMID 36686796, 2022). "Foremost, GRB7 inhibition has strong anti‐tumour activity and pursuing it in clinical practice as a therapeutic target could provide an advantage in future cancer treatment." (PMID 32737994, 2020). "Thus, from the functionally important GRB7 interaction partners, it is likely that GRB7 is increasing the oncogenic potential of cancer cells by sustaining cell growth, preventing apoptosis, and either acquiring or potentiating migration capabilities." (PMID 32737994, 2020). "Targeting Grb7-mediated signaling has also been indicated in cancer therapy." (PMID 31083325, 2019). "Moreover, an interaction between Grb7 and calmodulin has been indicated in the regulation of cell angiogenic activity, suggesting a critical role of Grb7 in cancer metastatic spread and the development of neovascularization." (PMID 31083325, 2019). "Additionally, shRNA or peptides targeting Grb7 expression or the SH2 phosphotyrosine binding site display promising anti-cancer effects in preclinical studies." (PMID 31083325, 2019). "Moreover, cosilencing of ERBB2 co-amplified genes, including ERBB2 and GRB7, results in increased apoptosis in cancers." (PMID 31083325, 2019). "Moreover, GRB7-mediated ERK/forkhead box M1 (FOXM1) signaling has been suggested to be an oncogenic convergence in the stimulation of cancer invasion." (PMID 31083325, 2019). "In different types and stages of cancers, the structural statuses and the phosphorylation statuses of Grb7 might also lead to a seemingly contradictory dual role of the SH2 domain of Grb7 in Grb7-mediated oncogenesis." (PMID 31083325, 2019). "Furthermore, Grb7 peptides targeting the SH2 domain of Grb7 impaired the phosphorylation of ERK 1/2 in EGF-stimulated cancers." (PMID 31083325, 2019).
cancer (continued). "Grb7 is an attractive target for the development of novel anti-cancer agents that may act on their own or in combination with other therapies." (PMID 31627265, 2019). "In agreement with the importance of the SH2 phosphotyrosine binding site of Grb7 in Grb7-mediated signal transduction cascades and cancer malignancy, the specific Grb7 peptide targeting the SH2 phosphotyrosine binding site of Grb7 efficiently blocks Grb7-mediated signal transduction cascades." (PMID 31083325, 2019). "Moreover, several ERBB family-mediated signals contribute to Grb7-mediated cell survival as well as anti-apoptosis in cancer cells." (PMID 31083325, 2019). "The expression of Grb7, one of the most important mediators in ERBB family-mediated signaling, is significantly correlated with cell cycle progression and anchorage-independent growth, highlighting Grb7 as a critical mediator in ERBB family-mediated cancer proliferation." (PMID 31083325, 2019). "Additionally, combination treatment with Grb7 peptide and Herceptin or doxorubicin display cooperative anti-cancer effects." (PMID 31083325, 2019). "Cooverexpression of Grb7 and ERBB2 are strongly associated with a worse prognosis than that of ERBB2 overexpression alone, suggesting the clinical significance of both Grb7 and ERBB2 genes/proteins expression in cancer development." (PMID 31083325, 2019). "Indeed, it has been shown that high Grb7 expressing cancer cells exhibit a higher migratory ability than low Grb7 expressing cells." (PMID 31083325, 2019). "Additionally, our studies and others have further investigated the EGF/EGFR-mediated tyrosine phosphorylation of Grb7 that is involved in aggressive and malignant features of cancers." (PMID 31083325, 2019). "Additionally, the finding of no significant deleterious effects of G7-18NATE on nonmalignant cells or animals suggests the long-term safety and well tolerability of peptides targeting Grb7 in patients with cancers." (PMID 31083325, 2019). "Recent reports suggest that ERBB2/GRB7 co-amplification may be a necessary step for cancer progression in specific cancer types, such as Barrett's carcinoma." (PMID 24874471, 2014). "Such nonphosphorylated peptides may be useful for rational design of drugs targeted against cancers that express high levels of Grb7 protein." (PMID 22253820, 2012). "These nonphosphorylated peptides may be optimized and useful for the rational design of drugs targeted against cancers that harbor increased Grb7 protein expression." (PMID 22253820, 2012). "Although all of these aberrantly activated factors are dominantly associated with cancer pathogenesis, there is no report so far to mention the signaling link amongst GRB7, ERK activity and FOXM1 in human cancer cells." (PMID 23285101, 2012). "Given to its important roles as signal transduction molecules in activating oncogenic signaling pathways, numerous studies have attempted to develop inhibitors targeting to the SH2 domain of GRB7 in order to inhibiting aberrant activation of related signaling activities and eliminating cancer cells." (PMID 23285101, 2012). "This site might be located between GRB7 and THRA, a gene located 315 kb from GRB7, given that 84 (97.7%) of the cancer specimens we assessed presented GRB7 amplification, whereas only 47 (54.7%) showed THRA amplification." (PMID 21288332, 2011). "To assess whether Grb7 upregulation due to lapatinib would occur in cancer cells in vivo, we made use of a BT474 murine xenograft model." (PMID 20126311, 2010). "Grb7 upregulation induced by lapatinib was found to occur in cancer cells in vitro and in vivo." (PMID 20126311, 2010). "Such a peptide provides the opportunity to test the role of Grb7 in cancer progression, and may potentially lead to novel anti-cancer therapeutics." (PMID 17894853, 2007).